ALK (ALK receptor tyrosine kinase)
Diseases named in the same sentence as ALK in open-access papers (continued):
Sharing a sentence is not in itself a finding about the gene and the disease.
lung cancer (continued). "Antitumor activity also has been observed in phase I and II clinical trials with ganetespib or IPI-504, and a number of Hsp90 inhibitors - both as monotherapies and in combination with ALK tyrosine kinase inhibitors - are undergoing clinical trials for ALK-positive lung cancer patients." (PMID 26219569, 2015). "Finally, we have described a subset of lung carcinomas harboring EGFR and ALK mutations and overexpressing p16Ink4A that shows better clinical outcome compared to p16Ink4A-wild-type tumors." (PMID 26674347, 2015). "This formation is biologically important as EML4 activates ALK kinase via mediating ligand-independent oligomerization of ALK, and the activated ALK is responsible for the growth and survival of lung cancer cell lines, the process being highly sensitive to ALK kinase inhibitors." (PMID 24959902, 2014). "IHC analysis of ALK in tumor specimens was performed on 525 lung cancer patients." (PMID 24667260, 2014). "These genes have all been shown to be partners of ALK in lung cancer." (PMID 25083769, 2014). "Both lung cancers with EGFR mutations or ALK translocations are characterized by negative or light smoking history." (PMID 24926563, 2014). "Thus, molecular detection of lung cancers for the critical predictive biomarkers, ALK and EGFR, has become imperative to select right patients for target therapies in the clinical practice." (PMID 24667320, 2014). "ALK1 has been reported to lack the sensitivity in ALK positive lung cancers." (PMID 24667320, 2014). "Clinical features and CT scan findings of advanced ALK-positive lung cancer." (PMID 24403104, 2014). "Lung cancers harboring ALK rearrangements represent a unique subpopulation of lung cancer patients." (PMID 25386659, 2014). "Kaplan-Meier survival curves demonstrated significantly reduced survival for N39-positive patients in each subset grouped by age, stage, EGFR/KRAS/ALK alteration status, and smoking history, with the exception of patients with stage II lung cancer, presumably reflecting the reduced sample size." (PMID 25146220, 2014). "EML4-ALK-positive lung cancers are highly sensitive to ALK inhibition." (PMID 24842630, 2014). "Additionally extending this view, we in this meta-analysis found that the relationship between ALK rearrangements and lung cancer histology was race-dependent." (PMID 24959902, 2014). "The results show that in ALK translocated lung cancer lines H3122 and H2228, cells with cancer stem-like cell features characterized by high expression of cancer stem cell markers and/or in vivo tumorigenesis can mediate adaptive resistance to oncogene ablative therapy." (PMID 25238228, 2014). "Perhaps one of the best examples is the identification and selection of sub-populations of lung cancer patients (between 2-7%) harboring molecular rearrangements in ALK who have demonstrated survival benefit with the use of ALK-targeting agents such as crizotinib." (PMID 25315999, 2014). "The aim of this study is to investigate the clinical pathological features of ALK positive lung cancer, and the roles of immunohistochemistry (IHC) and fluorescence in situ hybridization (FISH) in screening and confirming the ALK positive cases in the testing flow of ALK." (PMID 24667260, 2014). "ALK-positive lung carcinoma was significantly predominant for male patients in this study." (PMID 25295103, 2014). "Out of the 14 cases, seven cases were identified as ALK-positive lung carcinoma." (PMID 25295103, 2014). "In addition, the interpretation of FISH for ALK in NSCLC tends to be difficult, as ALK-positive lung carcinoma possesses an intrachromosomal rearrangement, resulting in a relatively close separation of the break-apart probes." (PMID 25295103, 2014). "Eight cases of ALK-positive lung carcinoma were found by IHC." (PMID 25295103, 2014). "In conclusion, a combination of the methodologies of IHC and FISH could be suitable for screening for ALK-positive lung carcinoma." (PMID 25295103, 2014).
lung cancer (continued). "We identified 44 cases of ALK-rearranged cases in 572 lung cancers." (PMID 23922677, 2013). "In addition to EML4, other ALK fusion partners have also been reported in lung cancer, including TFG, KIF5B, and KLC1." (PMID 23484153, 2013). "For lung cancers, the genomic panel comprises of ALK, EGFR, KRAS and BRAF." (PMID 23863689, 2013). "ROS1 rearrangements also define a unique molecular subclass of lung cancer that may respond to an ALK inhibitor." (PMID 24261984, 2013). "However, the results of ALK IHC testing in lung cancer remains to be unsatisfied because of relatively low sensitivity or specificity, and absence of an ideal antibody." (PMID 23922677, 2013). "HM has found ALK fusion in lung cancer with own developed cDNA library." (PMID 23289484, 2013). "We sought to compare the clincopathologic features of ALK-rearranged lung cancer with the common driver mutations and pan-negative tumors." (PMID 23922677, 2013). "Furthermore, we aimed to ascertain the potential of targeted resequencing in detection of ALK-rearranged lung carcinomas." (PMID 23484153, 2013). "In fact, for several actionable molecular abnormalities, including ALK rearrangements, the median age of onset may be several years younger than for the general lung cancer population." (PMID 22374459, 2012). "Identification of a small fraction of lung cancers patients responsive to a molecular target therapy may have large clinical impact as highlighted by the recent FDA approval of crizotinib for ALK-rearrangement lung cancers." (PMID 23342255, 2012). "Moreover, in 2007 the existence of the echinoderm microtubule-associated protein-like 4-anaplastic lymphoma kinase (EML4-ALK) fusion gene was discovered in NSCLC, and the same as EGFR-TKIs, ALK inhibitors are being found to be highly effective in lung cancers." (PMID 22989458, 2012). "HSP90 inhibitors have been hypothesized to be active preclinically in a wide variety of tumor types but clinically have shown objective tumor responses in HER2 positive breast cancer and most recently in ALK+ lung cancer." (PMID 24280702, 2012). "The most frequent ALK fusion in lung cancer is EML4-ALK (4–7%), and the second is KIF5B-ALK (0.5%)." (PMID 22347464, 2012). "Therefore, it is interesting that all the 3 ALK fusions in lung cancer are likely to colocalize with microtubules." (PMID 22347464, 2012). "EML4-ALK, EGFR, and KRAS mutations were all mutually exclusive, suggesting that ALK mutation may be an important oncogenic factor, and a potential therapeutic target in EGFR wild-type and KRAS wild-type lung cancer." (PMID 21444946, 2011). "Using this method, we analysed the ALK fusion status in clinical lung cancer samples." (PMID 20624322, 2010). "Importantly, in some cell lines harboring EML4-ALK fusions, targeting of ALK using specific inhibitors has shown promising efficacy for treatment of lung cancer through inhibition of Akt and induction of apoptosis." (PMID 20624322, 2010). "Moreover, multi-omics data has demonstrated significant efficacy of ALK-targeted drugs (such as crizotinib) in ALK-positive lung cancer patients, improving overall survival, highlighting the powerful role of multi-omics strategies in precision therapy for patients with lung cancer." (PMID 41269529, 2025). "Given the increasing reliance on genetic and biomarker testing (EGFR, ALK, ROS1, PD-L1, and KRAS mutations) for targeted treatments, the ability to perform molecular analysis on minimally invasive samples represents a significant advancement in lung cancer care." (PMID 40805957, 2025). "Although ALK inhibitors are the tyrosine kinase inhibitors (TKIs) with the longest survival rates in lung cancer, the complex systemic clinical evaluation and the apoptotic cell death evasion of drug-tolerant persister (DTP) cancer cells may limit their therapeutic response." (PMID 40113795, 2025). "Importantly, RDAA lung cancer cells exhibit marked sensitivity to FDA-approved ALK inhibitors." (PMID 40246819, 2025).
lung cancer (continued). "However, hematoxylin and eosin staining often fails to detect mutations, except in cases such as ALK fusion lung cancer." (PMID 40218244, 2025). "Therapeutic advances in treatment of lung cancer have included targeted therapies, which are available for patients with mutations in oncogenes such as ROS Proto-Oncogene 1 (ROS1), epidermal growth factor receptor (EGFR), anaplastic lymphoma kinase (ALK), and B-raf proto-oncogene (BRAF)." (PMID 41316207, 2025). "Therefore, therapeutic strategies aimed at enhancing immune cell activity - such as combining ICIs with ALK-targeted agents - may help overcome resistance and improve outcomes in lung cancer patients." (PMID 40873540, 2025). "The clinical features of lung cancers carrying mutations in the echinoderm microtubule associated protein-like (EML4)-ALK fusion gene include mild or never smoking, younger age, adenocarcinoma with an alveolar pattern or impression ring adenocarcinoma, and lack of EGFR or KRAS mutations." (PMID 40136367, 2025). "A deeper understanding of ALK-targeted therapy resistance is critical for developing new treatment strategies and may provide important insights to guide the diagnosis, treatment, and management of patients with resistant ALK+ lung cancer." (PMID 40873540, 2025). "However, EGFR-mutated and ALK-rearranged lung cancers represent no more than 15% of patients with lung cancer." (PMID 39123495, 2024). "Similarly, dual ALK‐MET inhibition may also overcome ALK‐positive lung cancer with MET‐driven resistance." (PMID 39184861, 2024). "Moreover, they compared ALK‐positive lung cancer with WT cancers, which included various types of NSCLC, even with another mutation‐positive lung cancer, which could diminish the characteristics of each driver mutation." (PMID 38400801, 2024). "Therefore, a response to an ALK-TKI may be expected if a patient from whom a tumor was established relapses with lung cancer." (PMID 38829559, 2024). "It is unknown whether all patients with ALK lung cancer should be treated with dual or triple therapy regimens, or whether this treatment paradigm should be reserved for a more select group of patients with ALK fusion–positive lung cancer." (PMID 39551860, 2024). "Our findings could aid in the efficient management of ALK‐positive lung cancer patients." (PMID 38171544, 2024). "Young patients with lung cancer also tend to have a greater number of oncogenic genomic alterations, including ALK and ROS rearrangements and ERBB2 (HER2) alterations (i.e., gene amplification or mutation), suggesting that this population may benefit from targeted therapy." (PMID 38750337, 2024). "Therefore, ceritinib’s inhibition of ALK may trigger an upsurge in Src signaling, and saracatinib could potentially serve as a therapeutic agent for treating lung cancer patients resistant to ALK inhibitors." (PMID 38397899, 2024). "For instance, it was reported that for lung carcinoma, the rate of EGFR testing was the highest (>80%) while the rates of ALK and ROS1 testing were remarkably lower, despite the fact that ALK and ROS1 mutations could occur in up to 10% of the cases." (PMID 38404964, 2024). "Additionally, median progression-free survival exceeds 9 months, and the median OS could reach 75% after 1-year crizotinib treatment in ALK-positive lung cancer patients." (PMID 37221218, 2023). "Especially among 4 patients harbouring EGFR or ALK mutation, 3 patients achieved partial response and 1 stable disease, which is in accordance with the prospective study evaluating the efficacy of EGFR TKI for the treatment of lung cancer patients with poor performance status." (PMID 37950224, 2023).
lung cancer (continued). "Young patients with lung cancer have unique clinicopathological and gene mutation characteristics, such as common in women, no smoking history, mainly adenocarcinoma, with advanced TNM stage, and prevalence of targeted genetic alterations such as ALK gene and EGFR gene mutations." (PMID 37009049, 2023). "Anaplastic lymphoma kinase (ALK) can be driven to oncogenic activity by different types of mutational events such as point‐mutations, for example F1174L in neuroblastoma, and gene fusions, for example with echinoderm microtubule‐associated protein‐like 4 (EML4) in non‐small cell lung cancer (NSCLC)." (PMID 37149843, 2023). "Hence, lung cancer patients with the EML4-ALK protein have been treated with ALK inhibitors." (PMID 36982897, 2023). "Interestingly, it has been recently reported that SHP2 inhibition can sensitize oncogene-addicted tumors to retreatment with targeted therapies, including ALK inhibitors, for ALK fusion–positive lung cancer; these effects were observed in preclinical models and patients." (PMID 38032104, 2023). "However, the molecular mechanism underlying the adaptive resistance to the new class of ALK-TKI, such as lorlatinib, in lung cancer cells remains unclear and requires further investigation." (PMID 36702855, 2023). "One review of lung cancer management in South Africa noted that for private sector patients with EGFR mutations, only erlotinib is available for first line use, osimertinib is available in the second line setting and crizotinib is the only drug available for ALK positive patients." (PMID 37368872, 2023). "The Leader trial (the Lung Cancer Mutation Consortium) has developed a collaborative protocol to screen patients suffering from stage IA2-IIIA NSCLC through tissue- or blood-NGS for assessing the incidence of 10 molecular gene drivers, including ALK, in early-stage disease (NCT04712877)." (PMID 37232842, 2023). "Perhaps the most striking recent improvements in lung cancer survival are seen among patients whose cancers are driven by a distinctive molecular event, the fusion between echinoderm microtubule‐associated protein‐like 4 (EML4) and anaplastic lymphoma kinase (ALK)." (PMID 37149843, 2023). "Furthermore, ALK fusions similar to lung cancer are an occasional driver in prostate cancer." (PMID 36337169, 2022). "The Anaplastic Lymphoma Kinase (ALK) is aberrantly is rearranged or mutated in several tumors including inflammatory myofibroblastic tumor (IMT), anaplastic large-cell lymphoma (ALCL), neuroblastoma, inflammatory myofbroblastic tumor and nonsmall cell lung cancer (NSCLC) patients." (PMID 36092663, 2022). "The simultaneous discovery of potential toxic effects of certain tyrosine kinase inhibitors in patients with ALK rearrangement who had received previous immunotherapy provides evidence for the need for further refinement of genetic testing before treatment of patients with lung cancer." (PMID 36591504, 2022). "Thus, the G12C and G12V alterations that are especially enriched in lung cancer are most commonly the result of smoking induced toxicity, rather than a single strong driving mutation such as ALK or EGFR." (PMID 36136862, 2022). "In vitro data presented here demonstrate that the ALK-overexpressing NEPC cell line MSKCC EF1 is sensitive to the ALK inhibitors crizotinib and ceritinib and show IC50 values similar to the ALK-rearranged lung cancer (H2228) or ALK-mutated neuroblastoma (SH-SY5Y) cell lines." (PMID 36337169, 2022). "EGFR and ALK tyrosine kinase inhibitors have demonstrated marked activity in lung cancers harboring driver mutations in these genes; however, these mutations are not driving features of smoking-associated lung cancer." (PMID 33754052, 2021). "The anaplastic lymphoma kinase (ALK) inhibitor ceritinib was found to be capable of modulating the protein-trafficking and degradation-related process of autophagy after the quantitative analysis of five lung cancer cell lines in response to more than 50 drugs." (PMID 34095463, 2021).
lung cancer (continued). "In addition, the next-generation ALKI, ceritinib, demonstrated significantly longer PFS and ORR compared to platinum-based chemotherapy in untreated ALK-positive advanced lung cancer patients in the ASCEND-4 trial (median PFS 16.6 vs. 8.1 months, HR = 0.55, p < 0.00001; ORR = 72.5% vs. 26.7%)." (PMID 33921762, 2021). "However, no survival difference was found between high and low TMB/MATH score in the whole lung cancer patients without EGFR or ALK mutations receiving first-line chemotherapy." (PMID 34604048, 2021). "qRT-PCR could define ALK fusion partners and variants and also could be a suitable method for detecting ALK translocations using cytology samples from patients with primary lung cancer, especially when tissue samples are not available." (PMID 33946969, 2021). "Those low frequencies of ALK rearrangement and BRAF mutations could be attributed to the type of samples in our study, as we only have surgical resection samples and most of the patients were at early stages of lung cancer." (PMID 33956842, 2021). "One explanation for this is that the co-occurrence of other genomic or epigenomic alterations with DDR mutations may dilute the influence of initial chemotherapy in lung cancer patients with no EGFR or ALK mutations." (PMID 34604048, 2021). "However, as exemplified by BCR-ABL1 in chronic myeloid leukemia and ALK fusions in lung carcinomas and mesenchymal tumors, gene fusions may play critical roles in tumorigenesis and present as attractive targets for therapeutic intervention." (PMID 33617877, 2021). "Hence, Dai and colleagues sought to investigate whether there are synergistic effects when combining radiotherapy and ALK‐inhibition via TAE684 in ALK‐positive versus wild‐ type lung cancer cells." (PMID 31799812, 2020). "ALK gene rearrangement occurs in a small portion of patients with non-small-cell lung cancer (NSCLC), but it accounts for about 30%–40% of lung adenocarcinoma in young individuals, and is present in many non-smokers and patients with epidermal growth factor receptor (EGFR)-mutated lung cancer." (PMID 32283823, 2020). "Thus, the ALK fusion has been considered as a very important lung cancer driver gene." (PMID 33157918, 2020). "Non-small-cell lung cancer (NSCLC) consists of nearly 85% of lung cancer cases and targeted therapeutics based on driver mutations of NSCLC, such as mutations of epidermal growth factor receptor (EGFR) and anaplastic lymphoma kinase (ALK), have significantly prolonged the survival of patients." (PMID 32611363, 2020). "However, the use of antiangiogenetic drugs and, more in general of targeted therapies, is increasingly growing in advanced diseases, thus resulting in long-term clinical benefit and disease control (e.g., anti-VEGFR and anti-EGFR in colorectal cancer, EGFR TKIs, and ALK inhibitors in lung cancer)." (PMID 31852067, 2019). "Also, miR-29a was found to be downregulated in many other types of neoplasms like lung cancer, oral squamous carcinoma, glioblastoma, metastatic prostate cancer, ALK-positive anaplastic large cell lymphomas, endocrine-sensitive breast cancer." (PMID 31870103, 2019). "Thus, according to recent clinical trials, ALK-positive lung cancer could be considered as the best subgroup in advanced-stage NSCLCs, showing good long-term survival when ALK TKIs are given as first-line treatment and continue to subsequent treatment." (PMID 31154543, 2019). "Therefore, a 75‐bp insertion between exons 24 and 25 besides EML4‐ALK rearrangement of resected primary lung cancer after second‐generation ALK‐TKI treatment may reflect a possible resistant mutation." (PMID 31285825, 2019). "In addition, both EGFR and ALK play pivotal roles in lung cancer pathogenesis." (PMID 30634502, 2019).